ALB (albumin)
Diseases named in the same sentence as ALB in open-access papers (continued):
Sharing a sentence is not in itself a finding about the gene and the disease.
tumor (continued). "These factors included elevated levels of body mass index, PD-L1 tumor proportion score (TPS), and albumin, as well as decreased levels of serum cytokeratin 19 fragment antigen 211, neuron-specific enolase, squamous cell carcinoma antigen, platelets, and C-reactive protein (all p < 0.05)." (PMID 39930148, 2025). "The combination therapy of sintilimab injection, albumin-bound paclitaxel, and cisplatin for stage IB–IIIB NSCLC can effectively reduce tumor marker levels, improve immune function, demonstrating favorable clinical and pathological efficacy without increasing the incidence of adverse drug reactions." (PMID 40103881, 2025). "In the present study, although the patients had advanced neoplasms, stratified mainly in stages III and IV of the TNM classification, and which presented an evolution to urgent clinical situations, the serum albumin values, on average, were below the values considered normal." (PMID 38324854, 2024). "Some of the detailed data such as BMI and AST, ALT, and albumin information was not accessible in previous real-world studies; moreover, potential confounders including hepatectomy records and anti-neoplasm agent use were also unconsidered." (PMID 38932232, 2024). "In this case, SON-1010 bound to albumin is pulled through the endothelial cells into the TME and is retained in that space by extracellular SPARC, giving the IL-12 extended time to activate the local immune response for better tumor control." (PMID 39697343, 2024). "As evident, CRP/albumin levels, while not negligible, are positioned lower in the ranking, akin to tumor-dependent variables." (PMID 39199720, 2024). "In their research, the lack of any chemical reactions preserved albumin bioactivities, and the albumin–pirarubicin complex showed greater tumor accumulation and tumor penetration through GP60- and SPARC-mediated biomimetic transport than pirarubicin and denatured albumin–pirarubicin." (PMID 38323081, 2024). "In the present study, patients with larger tumor diameters but high serum albumin and high PT% did not deteriorate to Child‐Pugh class B after TACE." (PMID 39487694, 2024). "Our previous work showed that biologically active albumin nanoparticles can effectively target solid tumors via GP60 and SPARC pathways and can effectively inhibit tumor growth and prolong the survival time of tumor-bearing mice." (PMID 38323081, 2024). "They used bovine serum albumin (BSA) as an “electronreservoir” to encapsulate the TADF photosensitizer PS, andthe integrated roles of the PS@BSA system showed excellent tumor-killingeffect for tumor-bearing mice in the in vivo experiments." (PMID 39744471, 2024). "For example, a 66-year-old patient with a Child-Pugh score of 6, his AFP at baseline is 792.6 ng/ml, ALB is 34.7 g/L, TBLT is 13.4μmol/L, largest tumor size is 4cm, tumor number is 2, by using our model, he got a survival rate at 1-, 3-, 5-year is 0.819, 0.519 and 0.386." (PMID 38434985, 2024). "This study aimed to investigate whether Hemoglobin, Albumin, Lymphocytes, and Platelets (HALP) score and Tumor Burden Score (TBS) serves as independent influencing factors following radical resection in patients with ICC." (PMID 38200585, 2024). "The tumor uptake of [177Lu]Lu-PSMA-TB-01 was higher than that previously reported for [177Lu]Lu-PSMA-617 and comparable to values of other known PSMA radioligands modified with moderately affine albumin binders." (PMID 38610940, 2024). "We conducted a subgroup analysis focusing on PNS, which unveiled notable distinctions between patients exhibiting erythrocytosis and those without such syndromes regarding tumor size, albumin levels, and AFP levels (p < 0.001)." (PMID 38674198, 2024). "Additionally, it acts as an anti-tumor agent by inhibiting SRC/MAPK/ERK pathways and regulating the expression of ALB, ESR1 and SRC." (PMID 39544939, 2024).
tumor (continued). "Albumin nanoparticles tend to accumulate in NSCLC due to the presence of GP-60 receptors in tumoral blood vessels and the overexpression of SPARC proteins in the tumour." (PMID 39771562, 2024). "For GP60 receptors and SPARC, SPARC was more frequently used to construct albumin-based drug carriers, which might be due to the reason that SPARC is directly expressed and secreted by tumor cells." (PMID 38323081, 2024). "The EGFR-Vδ2hi-lo bsVHH-albumin retained the ability to support Vγ9Vδ2 T-cell enrichment and expansion in healthy donor PBMC and also triggered Vγ9Vδ2 T-cell degranulation and lysis of SW480 tumor cells." (PMID 39493452, 2024). "Rats that were fed an HSHF diet for either 9 or 12 weeks displayed a notable increase in serum liver enzymes (ALT, AST, ALP, albumin, GGT, total bilirubin, direct bilirubin) and lipid profile (TC, TG, and LDL-C), along with elevated levels of the AFP tumor marker." (PMID 39182075, 2024). "The mIL12-FHAB anti-tumor activity was markedly enhanced, which was likely a result of the extension of half-life by linking the cytokine to the FHAB domain with subsequent binding to albumin." (PMID 39697343, 2024). "The albumin promotor becomes activated in neonatal mice proximal to DEN administration, thus it was unclear whether the increased tumour phenotypes in DKO mice could be due to ACC inhibition altering the process of carcinogenesis." (PMID 39538356, 2024). "The combined action of ALB and TNF-α affects tumor progression and improves patient survival." (PMID 37505298, 2024). "The TIIN score, derived from albumin-to-alkaline phosphatase ratio (AAPR), albumin–globulin ratio (AGR), monocyte-to-lymphocyte ratio (MLR), and tumor burden score (TBS), effectively categorized patients into high-risk and low-risk groups using the optimal cutoff value." (PMID 38783240, 2024). "Previous studies have suggested the possibility of an important pathway for albumin to pass through the BBB, as SPARC expression was maintained at a relatively low level in normal BBB capillaries, whereas it was upregulated by the tumor-derived secreted factor." (PMID 36945032, 2023). "cRGD-MID-AC and MID-AC contain albumin as the DDS, and the accumulation of sufficient boron concentration in tumor cells may result from the albumin conjugate in addition to the MID properties." (PMID 36979069, 2023). "Menthol-modified albumin nanoparticles were also effective in inducing apoptosis in tumor cells and were found to be safe for normal cells without causing organ toxicity in vivo." (PMID 37836018, 2023). "In the last several years, the Hemoglobin, Albumin, Lymphocyte, Platelet Score (HALP) has emerged in the literature as a new prognostic biomarker that has been used to predict a number of clinical outcomes in the context of various neoplasms." (PMID 36848404, 2023). "Karayama and colleagues found that increased GNRI, which was calculated from body weight and serum albumin, was associated with better PFS and OS in patients with NSCLC who received nivolumab, regardless of tumor PD‐L1 expression or ECOG‐PS." (PMID 38088761, 2023). "Secondly, this study did not include tumor-related indicators, albumin to globulin ratio, and lymphocyte to monocyte ratio, which will be further analyzed in subsequent studies." (PMID 37746281, 2023). "Moreover, the IOSS, age, A/G (Albumin/Globulin), PALB (prealbumin), FIB (fibrinogen), TLN (total lymph node), and tumor size were authenticated as potential independent factors to determine the OS." (PMID 37334172, 2023). "The enrolled factors for DFS included IOSS, PALB (prealbumin), TLN (total lymph node), tumor size, and postoperative chemotherapy; and for OS included IOSS, age, A/G (Albumin/Globulin), PALB (prealbumin), FIB (fibrinogen), TLN (total lymph node), and tumor size via the multivariate analysis." (PMID 37334172, 2023).
tumor (continued). "If PNA distributes similarly to endogenous albumin and the BBB isn’t appreciably leaky, then PNA within the CSF would be ~0.25 μM in our experiments, 100-480 fold lower than the concentrations effective in suppressing tumor cell proliferation." (PMID 37213306, 2023). "For example, negative correlations between serum albumin levels and tumor diameter, tumor multifocality, portal vein thrombosis, and α-fetoprotein, have been reported." (PMID 36835122, 2023). "Therefore, in this study, we used tumor regression grade (TRG) grading to evaluate the efficacy and safety of albumin-bound paclitaxel combined with nedaplatin in neoadjuvant therapy for ESCC." (PMID 36862884, 2023). "Therefore, apart from the laboratory tests and tumor characteristics, several inflammatory-based prognostic indices (NLR, PLR, SII, SIRI, hsCRP/ALB and PNI) were also included in this study." (PMID 37305570, 2023). "A systematic review and meta-analysis including mainly retrospective studies investigated the prognostic value of markers of the systemic inflammatory response in patients with advanced cancer, revealing that albumin and NLR have an independent prognostic value across different tumor types." (PMID 37370816, 2023). "All of the baseline characteristics were well balanced between the two groups including age, gender, BCLC stage, Child-Pugh class, albumin–bilirubin (ALBI) grade, PS score, tumor number, largest size, AFP level, portal vein tumor thrombus (PVTT), and extrahepatic spread." (PMID 38074645, 2023). "Bilirubin, albumin, Child–Pugh, or ALBI scores were not statistically associated with tumor response." (PMID 37510175, 2023). "Significant differences in each treatment group were observed in age, sex, high-risk (perineural invasion, lymphovascular invasion, perforation, poor differentiation, T4 lesion, harvesting < 12 lymph nodes), tumor location (rectum), CEA level, and nutritional status (albumin level)." (PMID 37749535, 2023). "Absence of extrahepatic metastases, <25% tumor burden, albumin > 3 g/dl, good performance status and receipt of < 2 chemotherapeutic medications are the independent predictors of survival." (PMID 37324012, 2023). "Compared to folate radioconjugates without an albumin binder, tumor uptake was increased and, at the same time, the otherwise exceedingly high kidney retention of the radioconjugate was considerably reduced." (PMID 37686538, 2023). "Multivariate analysis revealed that albumin (HR: 1.451, p < 0.001), creatinine (HR: 1.270, p = 0.003), AFP > 200 ng/mL (HR: 1.709, p < 0.001), vascular invasion (HR: 1.673, p < 0.001) and tumor size > 5 cm (HR: 1.855, p < 0.001) were independent predictors associated with shortened survival." (PMID 37046586, 2023). "combined NLR, serum albumin levels, and body mass index (BMI) into a subsequently, it was discovered that ALI may be beneficial for predicting survival outcomes in different tumours." (PMID 36998452, 2023). "IOSS is a nonspecific tumor predictor based on procurable oxidative stress index, comprising ALB (albumin), DBIL (direct bilirubin), and BUN (blood urea nitrogen)." (PMID 37334172, 2023). "Albumin is a highly abundantprotein in blood, meaning that once in circulation, complexes mightbind to HSA and be delivered to tumor cells." (PMID 37311060, 2023). "Furthermore, a system consisting of gold nanoparticles and organic molecules, such as bovine serum albumin (BSA), results in a higher agglomeration of nanoparticles in the tumor site." (PMID 37947732, 2023).
tumor (continued). "With the exception of age, body mass index, tumor size, ALB, NLR, PLR, and MLR were found to have non-normal distributions, as determined by the Shapiro–Wilk test." (PMID 37266630, 2023). "The CT scan showed a decrease in metastasis size, no ascites drainage was needed, and albumin and hemoglobin returned to normal values, which indicates tumor response." (PMID 37111635, 2023). "Performance status ≥ 1, low baseline albumin and sum of tumour diameters were identified as negative survival predictors, confirming previously reported results." (PMID 36764953, 2023). "Finally, AST, ALB, DBIL, maximum tumor size, numbers of tumors, HAVF, PVTT and integrality of the tumor capsule were selected for the multivariate logistic regression analysis." (PMID 37847433, 2023). "In the present study, the association of OPN with tumor burden was also proven by a strong positive correlation with B2MG and a weak negative correlation with albumin and hemoglobin." (PMID 38067265, 2023). "The liver function test shows no increase in albumin and globulin in controls and tumor-bearing constructs." (PMID 37359373, 2023). "In our previous study, bovine serum albumin (BSA) was employed as an organic reference to produce BSA/MnO2 NPs through biomimetic mineralization, a green, facile, and promising strategy to synthesize NPs for tumor therapy." (PMID 36909187, 2023). "In addition, OS was related to sex, ALB, HCIPS, surgery, tumor number, tumor size, BCLC stage, and TNM stage (all P < 0.05), while HCIPS, tumor size, and TNM stage were also the independent prognostic markers for OS." (PMID 38041022, 2023). "During the training phase of the model, univariate analysis indicated that the CRP to albumin ratio, postoperative CRP, lymphocytes, surgical duration, postoperative albumin, pre-operative red blood cells, tumor size, TNM, and ASA score were major predictive factors for anastomotic leakage." (PMID 35953684, 2023). "A ROS-responsive albumin-based system has been developed to sequentially release antibodies against CD47 and PD1, promoting M1 TAM differentiation and leading to an enhanced anti-tumor response." (PMID 38258072, 2023). "The thiolation‐and‐conjugation method did not affect the in vivo tumor targeting ability of albumin in a human triple‐negative breast cancer model." (PMID 36684090, 2023). "The PROSASH and PROSASH-II model, which consisted of serum albumin, bilirubin, AFP, macrovascular invasion, extrahepatic spread, and largest tumor size, could predict the survival of patients with HCC treated with sorafenib." (PMID 36910622, 2023). "The AUC of the tumor uptake and absorbed dose was higher for [177Lu]Lu-FAPI-46-F1D and the two albumin binder conjugates, [177Lu]Lu-FAPI-46-Ibu and [177Lu]Lu-FAPI-46-EB, in HT1080.hFAP xenografts and for [177Lu]Lu-FAPI-46-EB and [177Lu]Lu-FAP-2286 in HEK293.hFAP xenografts." (PMID 37261473, 2023). "Thus, cRGD-MID-AC, which has human serum albumin as a DDS and integrin αvβ3 as a tumor-targeting system, has been developed." (PMID 36979069, 2023). "Analysis of a flush sample demonstrated that these metabolites were present in the baseline sample, likely pre-bound to the utilized albumin, and did not reflect improved recovery from the tumor microenvironment via use of albumin-containing perfusate." (PMID 38115038, 2023). "In contrast, the treatment may be ineffective if the tumor has a GPS of 2 points, such as high CRP and low albumin levels at treatment initiation." (PMID 36741711, 2022). "Simultaneous planar imaging will be used to learn about the potential dynamic uptake behavior of 99mTc-macroaggregated albumin (MAA) particles and a SPECT/CBCT scan will be made to determine dosimetric measures (e.g., the lung-shunting fraction and tumor uptake ratios)." (PMID 34132877, 2022). "However, age, tumor diameter, tumor location, WBC, hemoglobin, fibrinogen, albumin, PNI, and NLR were invalid." (PMID 35340978, 2022).
tumor (continued). "These 68Ga radiopharmaceuticals include agents such as [68Ga]Ga-macroaggregated albumin for myocardial perfusion evaluation, [68Ga]Ga-PLED for assessing renal function, [68Ga]Ga-t-butyl-HBED for assessing liver function, and [68Ga]Ga-PSMA for tumor imaging." (PMID 36271969, 2022). "The following 12 variables related to the prognosis of HCC were considered at the start of the follow-up: age, sex, etiology, Child–Pugh class, tumor size, BCLC stage, albumin level, total bilirubin level, ALBI score, prothrombin time, AFP level, and DCP level." (PMID 35329809, 2022). "recently designed an albumin nanoparticle containing PI3Kγ inhibitor (IPI‐549) and paclitaxel (PTX), which remodeled the TAM in both tumor‐dLNs and tumor sites via the repolarization of M2 to M1 phenotype, thereby regressing metastatic breast cancer in murine models." (PMID 36257824, 2022). "In addition to demographics and crucial symptoms, our model included laboratory test results and tumor-related characteristics shown on ultrasound, such as γ-GGT, ET, and levels of bicarbonate, albumin, alkaline phosphatase." (PMID 35308550, 2022). "HER-2 status, tumor location, disease stage, albumin and hemoglobin values, and tumor marker levels did not have any effect on survival, consistent with the literature." (PMID 36326360, 2022). "In addition, the fibrinogen-to-albumin ratio (FAR) and D-dimer were reported to be involved in tumor progression." (PMID 35448194, 2022). "Exclusion criteria was if animals did not develop tumour (M-spike levels equal or higher than serum albumin levels)." (PMID 36435864, 2022). "Tumor tissues present leaky vasculature and the absence of lymphatic drainage, which allows albumin to extravasate into the tumor tissue, being retained with high intratumor concentrations." (PMID 35203695, 2022). "We evaluated the ligands in comparison with reference ligands [177Lu]Lu-PSMA-617 and [177Lu]Lu-PSMA I&T in vitro (lipophilicity, half-maximal inhibitory concentration, internalization into LNCaP cells, binding to human serum albumin [HSA]) and in biodistribution studies on LNCaP tumor–bearing mice." (PMID 35086894, 2022). "Albumin (ALB) is the most abundant plasma protein synthesized by the liver, with additional functions related to anticoagulation and anti-inflammatory, thereby inhibiting the growth of tumor cells." (PMID 35086516, 2022). "The effects of cytokine and protein stabilizing carriers, such as serum albumin, on tumor response to immune checkpoint blockade (ICB) is not well understood." (PMID 35393553, 2022). "We hope that our particles, characterized by peroxidase-like properties and a stable albumin coating obtained without toxic cross-linkers, demonstrating the long-term presence in tumor, are suitable for in vivo multimodal imaging and theranostics." (PMID 36559265, 2022). "In conclusion, we successfully confirmed 14 features closely related to dMMR in CRC patients: age, sex, HB level, platelet count, albumin level, globulin level, lymphocyte ratio, eosinophil ratio, NLR, CA125 level, primary site, histologic tumor grade, tumor type, and tumor volume." (PMID 36620593, 2022). "However, there has been limited coverage of ALB, LYZ and S100A14 in the field of PC, especially in the tumor immune microenvironment." (PMID 35953822, 2022). "In addition to operation duration, gender, age, pTNM, tumor site, histological type, EMVI, PNI, CRM, hemoglobin, albumin, and number of lymph nodes extracted were all significantly associated with OS, and with DFS (P<0.001)." (PMID 35281851, 2022).